EGF (epidermal growth factor)
Diseases named in the same sentence as EGF in open-access papers (continued):
Sharing a sentence is not in itself a finding about the gene and the disease.
gastric cancer (continued). "Specifically, TSPAN8 mediates the effect of EGF and actives the ERK MAPK pathway to promote gastric cancer cell proliferation." (PMID 34222025, 2021). "On the other hand, increased invasion of gastric cancer cells can occur in response to oxaliplatin through ATXN2L up-regulation, known as the regulator of SGs, with the effect of EGF along with the PI3 / AKT signaling pathway." (PMID 34604242, 2021). "In the present study, we showed that EGF- or serum-induced cell migration was greatly diminished after MICAL2 depletion, suggesting that MICAL2 plays a key role in the migration of gastric cancer cells." (PMID 33842533, 2021). "We found that TFBG partly suppressed EGF-induced Shc1 and SHCBP1 dissociation, which suggested that the feedback inhibition on Shc1–SHCBP1 of TFBG is one of the reasons why TFBG sensitize gastric cancer to trastuzumab." (PMID 33990570, 2021). "The upregulation of epidermal growth factor (EGF), its receptor (EGFR), and ErbB2 protein in gastric mucosa plays an important role in the occurrence and development of gastric cancer." (PMID 34824590, 2021). "Collectively, these data indicated that ROS generation by MICAL2 promotes EGF-induced MRTF-A nuclear import and gastric cancer cell migration." (PMID 33842533, 2021). "In gastric cancer, NRP1 also acts as a receptor for major signaling pathways including vascular endothelial growth factor (VEGF), epidermal growth factor (EGF), and semaphorin-3A (SEMA3), showing an important role in tumor development and metastasis." (PMID 32408477, 2020). "Nicotine and NNK act as agonist of α7-nAChR to facilitate the migration of gastric cancer cells and indirectly activate ERK signaling through promoting the release of epidermal growth factor (EGF) and trans-activation of EGF receptors." (PMID 31640627, 2019). "The protein is involved in several oncogenic signaling pathways, such as the Wnt/β-catenin, Rho GTPase, and EGF/EGFR, whereby it plays a role in many tumors, including gastric cancer." (PMID 31212809, 2019). "Knockdown of WWTR1 in the gastric cancer AGS cells resulted in severe impairment in both the basal and the EGF-stimulated cell migration." (PMID 30976198, 2019). "In this study we demonstrated for the first time that EGF stimulates EGFR and activates Rab35 via DENND1A in gastric cancer cells." (PMID 30524285, 2018). "We previously examined the effects of EGF and cetuximab treatment for 3 min on the expression and activation level of EGFR in gastric cancer cell lines." (PMID 29237412, 2017). "Recent reports indicated that EGF and its receptor EGFR were increased in some tumors, such as gastric cancer, and GBM, which further induced tumorigenesis, and stimulated cell proliferation and migration." (PMID 29254162, 2017). "To investigate the effects of exogenous ligands on the trastuzumab sensitivity of gastric cancer cells, we performed a concomitant treatment of gastric cancer cell lines with AREG, EGF or HB-EGF and trastuzumab." (PMID 27933395, 2017). "Treatment of AGS cells with epidermal growth factor (EGF) induced a marked increase in AGS cell migration and invasion, suggesting that EGFR signaling is involved in gastric cancer metastasis." (PMID 27105510, 2016). "EGF has been shown to be a potent pro-migratory factor for a variety of cultured gastric cancer cells, and EGFR is highly expressed in gastric cancer." (PMID 25779663, 2015). "A randomized phase III trial investigating the addition of nimotuzumab (a monoclonal antibody to EGF), to irinotecan as second line treatment of EGFR overexpressing gastric cancers is now ongoing (ENRICH, ClinicalTrials.gov identifier NCT01813253)." (PMID 25649416, 2015). "The ‘EGF- and HGF-dependent stimulation of metastasis in gastric cancer’ map revealed upregulation of HGF and its receptor MET." (PMID 24204627, 2013).
gastric cancer (continued). "Further study in our laboratory revealed that PKG II was able to inhibit EGF-induced proliferation and migration, and inhibit MAPK-mediated signal transduction in gastric cancer cells." (PMID 24273605, 2013). "The present study revealed that in gastric cancer cells, PKG II is able to inhibit the EGF/EGFR-induced signal transduction of the PI3K/Akt-mediated pathway and reverse the anti-apoptotic effects of EGF/EGFR." (PMID 24273605, 2013). "We used a defined serum-free medium consisting of EGF, FGF-2, B-27 supplement and N-2 supplement to maintain gastric cancer cell lines." (PMID 21394208, 2011). "In conclusion, cetuximab in combination with mFOLFOX6 as a first-line treatment in gastric cancer showed the most promising results in patients with EGFR expression and low serum ligand levels (EGF and TGF-α)." (PMID 19127259, 2009). "In summary, we have shown that EGF and EGF-R play a role in the regulation of NRP-1 and VEGF expression via multiple signalling pathways in human gastric cancer cells." (PMID 12618892, 2003). "To analyse the regulation of NRP-1 expression by EGF, we studied NCI-N87 and ST-2 human gastric cancer cells, which expressed relatively high levels of EGF-R." (PMID 12618892, 2003). "In the present study, we examined the expression of NRP-1 and EGF-R and the effect of EGF on NRP-1 and VEGF expression in human gastric cancer cells." (PMID 12618892, 2003). "Moreover, FLOT1 mediates the levels of heterotypic signaling molecules, including TNF-α, EGF, HGF, and IGF1, across various cancers, such as breast, prostate, and gastric cancer, and oral squamous cell carcinoma." (PMID 40335491, 2025). "In addition, it was clarified that epidermal growth factor (EGF) induced the upregulation of ZEB1 and ZEB2 via the Akt signaling pathway in gastric carcinoma, which was consistent with the results of our research." (PMID 40510028, 2025). "EGF can promote Ataxin-2-like (ATXN2L) as a stress granule regulator in the PI3/AKT signaling pathway, leading to oxaliplatin resistance and eventually increased cell invasion in gastric cancer." (PMID 35004322, 2021). "In another study, levels of EGF, EGFR and a homolog of EGFR (c-erb-B2) were shown to be elevated in gastric mucosa of patients suffering from chronic gastritis with a Helicobacter pylori infection, and were comparable to samples from gastric cancer patients." (PMID 32302357, 2020). "Treatment of the control shRNA cell line with EGF induced a marked increase in cell migration, suggesting that EGF receptor (EGFR) signaling might be involved in gastric cancer metastasis." (PMID 30976198, 2019). "A recent study has shown that some gastric cancer cell lines including AGS are resistant or partially resistant to treatment of cetuximab, an inhibitory EGFR antibody for treatment of metastatic colorectal cancer, on EGF-stimulated cell migration and invasion." (PMID 30976198, 2019). "This study aimed to describe the prognostic importance of epidermal growth factor (EGFR), phosphatase and tensin homolog (PTEN), human EGF receptor-2 (HER-2), and insulin-like growth factor 1 receptor (IGF-1R) in gastric cancer patients treated with postoperative chemoradiation therapy." (PMID 31318186, 2019). "In our study, only HB-EGF, but not AREG or EGF, rescued sensitive gastric cancer cell lines from trastuzumab and cetuximab treatment." (PMID 27933395, 2017). "For our analyses, we concentrated mainly on AREG, HB-EGF and TGFα, as previous results from our group had shown the absence of EGF secretion in gastric cancer cell lines." (PMID 27933395, 2017). "Further experimental results show that erlotinib pretreatment also prevented EGF-induced Rab35 activity in HeLa cells as well as in the gastric cancer cell line SGC-7901 (data not shown)." (PMID 29018350, 2017).
gastric cancer (continued). "The results obtained in this study clearly established a novel relationship between CD24 and EGF/EGFR signaling in the context of migration regulation, which could be essential in promoting aggressiveness of gastric cancer." (PMID 26830684, 2016). "We also noticed that Arf6-T27N expression significantly suppressed ERK phosphoyrlation by EGF, suggesting that ERK might act as a downstream effector of Arf6 in mediating EGF-stimulated gastric cancer cell EMT." (PMID 25779663, 2015). "Accordingly, we speculated that EGF/Arf6 signals might be able to repress Wnt5a transcription directly, thereby allowing EMT in gastric cancer cells." (PMID 25779663, 2015). "For the inhibition of PKG II on EGF/EGFR induced MAPK/ERK-mediated signal transduction pathway, our previous work have shown that PKG II inhibits the activation of all key components in the pathway induced by EGF in gastric cancer cell line BGC-823." (PMID 23613900, 2013). "Further study in our laboratory showed that PKG II could inhibit the proliferation of gastric cancer cell lines and block EGF induced signal transduction of MAPK/ERK-mediated pathway through preventing the activation of EGFR by EGF." (PMID 23613900, 2013). "We hypothesized that EGF, as a regulator of other angiogenic factors such as VEGF in other tumour types, regulates both VEGF and NRP-1 in human gastric cancer cell lines." (PMID 12618892, 2003). "They observed that the levels of this vitamin were correlated with the mRNA expression of the transmembrane protein with epidermal growth factor- (EGF-) like and two follistatin-like domains 2 (TMEFF2) in gastric cancer (GC) patients." (PMID 31934267, 2019). "Furthermore, we found that EGF stimulated AGS cell migration and knockdown of WWTR1 impairs both EGF-stimulated and EGF-independent AGS cell migration, suggesting that WWTR1 might mediate both EGFR-dependent and –independent gastric cancer cell migration." (PMID 30976198, 2019). "The experiments showed that EGF almost instantaneously induces a considerable increase in membrane ruffling and lamellipodial activity that can be inhibited by Cetuximab EGF receptor antibodies and is not elicited in non-responsive gastric carcinoma Hs746T cells." (PMID 23028903, 2012). "A recent study has shown that EGF induces NRP-1 mRNA expression in astrocytoma, but the expression and regulation of NRP-1 in gastric cancer has not previously been investigated." (PMID 12618892, 2003).
colorectal cancer (117 papers, 1990 to 2025). A primary or metastatic malignant neoplasm that affects the colon or rectum. "The presence of FOXK2 is linked to the metastasis of colorectal cancer, and the drug cetuximab can disrupt the feedback loop involving EGF NF‐κB–FOXK2–EGFR, thus preventing metastasis in CRC." (PMID 39552461, 2024). "In colorectal cancer, the aberrant activation of epidermal growth factor (EGF) disrupts the association between E-cadherin and β-catenin, increasing cell proliferation and migration." (PMID 36836894, 2023). "Meanwhile, the effect of EGF is recently linked to the activation of ERK1/2 to promote serine biosynthetic flux from glycolysis but only in colorectal cancer." (PMID 35122791, 2022). "EGF is upregulated nearly 3-fold in colorectal carcinoma and the EGF signaling pathway is intimately linked to promotion of solid tumor growth." (PMID 23861820, 2013). "The strength of cell-autonomous growth signals can vary depending on the mutations or epigenetic changes in individual colorectal cancer cases, which may explain why some spheroid lines were difficult to be maintained even in the presence of EGF and bFGF." (PMID 29774115, 2018). "A previous study has demonstrated that the methylations on the EGFR extracellular domain mediated by PRMT1 enhance receptor function in colorectal cancer cells, affecting the EGF-EGFR binding affinity to promote tumorigenesis." (PMID 40612681, 2025). "In colorectal cancer cells, EGF decreases expression of the fatty acid transporter intestinal fatty acid binding protein (I-FABP) and fatty acid uptake while increasing FAS expression, and intracellular TG and cholesterol content." (PMID 39433211, 2025). "The RAS gene is also an important target for colorectal cancer treatment, and KRAS mutation status can predict the therapeutic effect of anti‐epidermal growth factor (EGFR)." (PMID 38698687, 2024). "For the less differentiated HCT116 cells, Tf leads to an increased binding of its epidermal growth factor (EGF) to its receptor, while more differentiated colorectal cancer cell lines exhibit the opposite effect." (PMID 38500764, 2024). "•Dimeric procyanidins inhibit epidermal growth factor (EGF)-induced colorectal cancer cell (CRC) invasion." (PMID 37516013, 2023). "In particular, the EGF/EGFR pathway caught our attention since EGFR has been shown to be overexpressed in colorectal cancer patient populations but its prognostic value in this tumor progression remains still unclear." (PMID 37853459, 2023). "A previous study revealed that epidermal growth factor (EGF) stimulation activated NF-κB via PLCγ1 in colorectal cancer cells." (PMID 37408216, 2023). "It is reported that the MAPK signaling pathway plays an important role in cell proliferation, and is commonly activated by its upstream growth-factor receptors, such as the epidermal growth factor which is commonly over-expressed in colorectal cancer." (PMID 36624500, 2023). "EGF targeting of λ phage enhances uptake into HT-29 colorectal cancer spheroids and facilitates cellular entry." (PMID 36591314, 2022). "Here, we used chemically defined medium containing EGF and bFGF-2, in accordance with the isolation of colorectal cancer stem-like cells as well as of adult human stem cells from the nasal cavity and the heart auricle." (PMID 33800955, 2021). "The downregulation of miR-217 expression by FAK inhibitors indicates that miR-217 is involved in the process of EGF-induced EMT in colorectal cancer cells." (PMID 32148496, 2020). "Its ability to bind to high-affinity EGFR ligands (e.g., HB-EGF, TGFα, BTC, and EGF) contributes to its anti-tumor efficacy against KRAS-mutant colorectal cancer (CRC) in a patient-derived xenograft (PDX) model resistant to cetuximab treatment." (PMID 33142709, 2020). "Adenoviral vectors encoding antibodies directed against epidermal growth factor (EGF), p21Ras or tissue factor were shown to afford significant benefits in murine colorectal cancer models." (PMID 32295072, 2020).
colorectal cancer (continued). "This indicated that the migration and invasion abilities of colorectal cancer cells were significantly enhanced by EGF treatment." (PMID 32148496, 2020). "At the same time, the observed increase in cell migration ability indicates that EGF enhances the metastasis of colorectal cancer cells." (PMID 32148496, 2020). "We found that EGF induced EMT in colorectal cancer cells and enhanced cell migration and invasion ability." (PMID 32148496, 2020). "FAK inhibitors can also inhibit the downregulation of E-cadherin and upregulation of vimentin in the process of EGF-induced EMT in colorectal cancer cells." (PMID 32148496, 2020). "After pretreatment with FAK inhibitor PF-228 (10 μM) for 1 hour, the migration and invasion abilities of EGF-induced colorectal cancer cells was determined by the transwell assay." (PMID 32148496, 2020). "Caco-2 colorectal cancer cells were treated with 100 ng/mL EGF for 24 hours, and changes in cell morphology were observed using an inverted microscope." (PMID 32148496, 2020). "Similar to another study, this study further demonstrated that EGF can induce EMT in colorectal cancer cells." (PMID 32148496, 2020). "In the other case report, a 62-year-old patient with colorectal cancer exhibiting multi-organ metastases was administered EGF eye drops (0.05 mg/ml, 8/day) to treat binocular refractory corneal epithelial defects during cetuximab treatment." (PMID 32295556, 2020). "As a result, epidermal growth factor (EGF), MAP2K2, MCC (mutated in colorectal cancer), and NRAS (neuroblastoma RAS viral oncogene homolog) were determined as remarkably prognostic-related genes." (PMID 33553243, 2020). "In this study, the role of miR-217 in colorectal cancer cells was further explored, and we found that EGF upregulates miR-217 by activating FAK, causing EMT in colorectal cancer cells and thereby enhancing the invasion and metastasis of colorectal cancer." (PMID 32148496, 2020). "In colorectal cancer cells, claudin 3 overexpression promoted the malignant potential of cells, probably via epidermal growth factor-activated ERK1/2 and PI3K-Akt pathways." (PMID 29482498, 2018). "KRAS-driven colorectal cancer is initiated from the epidermal growth factor (EGF) binding to the EGF receptor (EGFR), which activates GTP-bound KRAS." (PMID 30577618, 2018). "To analyze the influence of Fas survival pathways on the EGFR signaling in cancer, we examined the EGF-induced activation of EGFR in two KRAS-mutated, cetuximab-resistant colorectal cancer cells, SW480 and HCT116." (PMID 30127519, 2018). "This important observation prompted us to investigate the connection between this pro-survival Fas in EGF-dependent EGFR signaling in colorectal cancer cells, which represents the type of cancer to which anti-EGFR therapy is widely applied." (PMID 30127519, 2018). "Conversely, upregulation of CLDN3 play fundamental role to promote the development of colorectal cancer, which is potentially regulated by the EGF-activated downstream pathway, ERK1/2 and PI3K-Akt signaling pathways." (PMID 28160565, 2017). "Expression of TGFα, EGF, and EGFR worsens prognosis and increases the metastatic potential of breast, renal, and colorectal cancers, all known to be obesity-associated malignancies." (PMID 27525640, 2017). "EGF was used as cell-cycle inducer since EGFR signaling promoted cell-cycle progression in colorectal cancer." (PMID 29108242, 2017). "The interconnected network of pathways downstream of the TGFβ, WNT and EGF-families of receptor ligands play an important role in colorectal cancer pathogenesis." (PMID 25671297, 2015). "A number of other pathway‐specific inhibitors exist for colorectal cancer, including the antivascular endothelial growth factor (VEGF) mAb bevacizumab, MEK inhibitors that target EGF pathway mutated cancers and cancer vaccines." (PMID 25627134, 2015).